OR8I2 (olfactory receptor family 8 subfamily I member 2)
Description:
Odorant receptor.
Synonyms: OR11-170
Tractability: Antibody: UniProt places it where antibodies can reach, with medium confidence; UniProt predicts a signal peptide or a membrane-spanning region; its Gene Ontology location is reachable by antibodies, with medium confidence.
Gene: Protein-coding gene on chromosome 11 (56,093,308 to 56,094,240, forward strand). Ensembl gene ENSG00000172154.
Subcellular location: Cell membrane
Pathways (Reactome):
Sensory Perception: Expression and translocation of olfactory receptors
Gene Ontology:
Molecular function: olfactory receptor activity; G protein-coupled receptor activity
Biological process: G protein-coupled receptor signaling pathway; sensory perception of smell; detection of chemical stimulus involved in sensory perception of smell
Cellular component: plasma membrane; membrane
Genetic constraint (gnomAD): Missense variants: 418 observed, 360.21 expected, observed/expected ratio (o/e) 1.16, 90% interval 1.07 to 1.26. Synonymous variants: 151 observed, 141.33 expected, observed/expected ratio (o/e) 1.07, 90% interval 0.94 to 1.22.
Homologues: Orthologues: chimpanzee OR8I2 (97% identical), macaque OR8I2 (91% identical), rat Or8i2 (86% identical), mouse Or8i2 (85% identical). Paralogues in human: OR8H1 (58% identical), OR8H3 (57% identical), OR8H2 (56% identical), OR8U3 (54% identical), OR5A1 (53% identical), OR8U1 (53% identical), OR8A1 (53% identical), OR5F1 (52% identical), OR5M11 (52% identical), OR5B12 (52% identical), OR5M10 (52% identical), OR8B4 (52% identical), and 84 more.